TM9SF3 (transmembrane 9 superfamily member 3)
Synonyms: SMBP; EP70-P-iso
Tractability: Antibody: UniProt predicts a signal peptide or a membrane-spanning region. PROTAC: ubiquitination databases record sites on it; its protein half-life has been measured.
Gene: Protein-coding gene on chromosome 10 (96,518,110 to 96,587,452, reverse strand). Ensembl gene ENSG00000077147.
Subcellular location: Membrane
Subcellular location (Human Protein Atlas): Vesicles; Golgi apparatus
Gene Ontology:
Biological process: protein localization to membrane
Cellular component: membrane
Genetic constraint (gnomAD): Loss-of-function variants: 9 observed, 59.94 expected, observed/expected ratio (o/e) 0.15, 90% interval 0.09 to 0.26. The upper end of that interval is the gene's LOEUF score, 0.26, which puts it in group 1 of 6, group 1 being the genes least tolerant of losing a copy. Missense variants: 484 observed, 675.35 expected, observed/expected ratio (o/e) 0.72, 90% interval 0.66 to 0.77. Synonymous variants: 226 observed, 233.63 expected, observed/expected ratio (o/e) 0.97, 90% interval 0.87 to 1.08.
Homologues: Orthologues: chimpanzee TM9SF3 (100% identical), macaque TM9SF3 (99% identical), rabbit TM9SF3 (99% identical), mouse Tm9sf3 (99% identical), guinea pig TM9SF3 (98% identical), pig TM9SF3 (96% identical), rat Tm9sf3 (95% identical), tropical clawed frog tm9sf3 (93% identical), dog TM9SF3 (92% identical), zebrafish tm9sf3 (92% identical), Drosophila melanogaster TM9SF3 (73% identical), Caenorhabditis elegans Y41D4A.4 (63% identical). Paralogues in human: TM9SF4 (36% identical), TM9SF1 (34% identical), TM9SF2 (33% identical).
Diseases named in the same sentence as TM9SF3 in open-access papers:
TM9SF3 is named in the same sentence as 7 diseases in open-access papers, as found by Europe PMC text mining. Sharing a sentence is not in itself a finding about the gene and the disease. The quoted sentences say what the papers report.
leukemia (1 paper, 2022). A malignant (clonal) hematologic disorder, involving hematopoietic stem cells and characterized by the presence of primitive or atypical myeloid or lymphoid cells in the bone marrow and the blood. "TM9SF3 and ATP2A2 were considered as proto-oncogenes in leukemia, triple-negative breast cancer and diffuse astrocytic tumor." (PMID 36733399, 2022).
lung carcinoma (1 paper, 2022). "Further verification of RAB1A and TM9SF3, whether they are highly expressed in lung cancer patients." (PMID 36101742, 2022).
cancer (6 papers, 2019 to 2025). A tumor composed of atypical neoplastic, often pleomorphic cells that invade other tissues. "mir-1193 has been found to inhibit the proliferation and invasion of cancer cells by directly acting on transmembrane 9 superfamily member 3 (TM9SF3) and insulin-like growth factor 2 mRNA binding protein 2 (IGF2BP2)." (PMID 35937294, 2022). "MiR-1193 was previously shown to suppress proliferation and invasion of cancer cells through directly targeting transmembrane 9 superfamily member 3 (TM9SF3), and insulin-like growth factor 2 mRNA binding protein 2 (IGF2BP2)." (PMID 33046105, 2020). "Therefore, we can speculate that miRNA-195-3p is regulated by upstream lncRNA, negatively regulates the expression of TM9SF3, and ultimately affects the occurrence and development of cancer cells in LUAD patients." (PMID 36101742, 2022). "We also discovered some unidentified regulators such as TM9SF3, LYZ, and ARL4C, which are potentially engaged in the cellular transition from the cancer stem cells into metastatic malignant cells." (PMID 34732701, 2021).
tumor (5 papers, 2022 to 2025). "Our results provide compelling evidence that TM9SF3 plays a role in the process of tumor metastasis to the brain." (PMID 39716938, 2025). "Analysis of the expression of this protein in clinical specimens showed high expression of TM9SF3 in triple-negative breast tumors when compared with the expression observed in tissues adjacent to the tumor." (PMID 38255914, 2024). "TM9SF3 is a nine-transmembrane protein that participates in tumor invasion and serves as a prognostic factor." (PMID 35711801, 2022). "We further validated the expression and subcellular localization of these hub proteins in tumor tissues by selectively performing IHC staining using antibodies against the NSUN2, TM9SF3 (transmembrane 9 superfamily member 3), and PKC (protein kinase C)." (PMID 39716938, 2025).
TM9SF3 also shares sentences with these, for which no sentence is quoted: fatty liver (1 paper); glioma (1); triple-negative breast carcinoma (1).